TNF (tumor necrosis factor)
Diseases named in the same sentence as TNF in open-access papers (continued):
Sharing a sentence is not in itself a finding about the gene and the disease.
depression (continued). "Depression is closely associated with altered inflammation, manifested by increased expression of inflammatory cytokines such as TNF-α and IL-6." (PMID 31672153, 2019). "Other works support the involvement of microglial activation in prefrontal cortex, amygdala, and hippocampal neurons associated with an overproduction of TNF in neuropathic pain and chronic-pain-associated depression." (PMID 32047493, 2019). "It has been reported that circulating IL-6 and TNF-α levels were significantly linked to patients with the severity of anxiety, depression and cognitive impairment." (PMID 31213027, 2019). "Depression is associated with the pro-inflammatory cytokine (IL-1, IL-6, and TNFα) via regulation of CRF." (PMID 31312123, 2019). "Both TNF-α and IL-10 were previously reported to be associated with depression, in which TNF-α is a pro-inflammatory cytokine, while IL-10 is an anti-inflammatory cytokine." (PMID 31881712, 2019). "TNF-α levels exhibited a weaker association with depression in patients with CFS than in healthy controls." (PMID 31253154, 2019). "A recent study reported an enhancement of circulating pro-inflammatory cytokines (including that of IL-2, IL-6, and TNF-α), which was associated with depression in patients with CFS." (PMID 31253154, 2019). "Elevated levels of TNF-α can activate 5-HT transporters and promote pre-synaptic reuptake of 5-HT, and this can lead to depression caused by a decrease in 5-HT levels in the synapse." (PMID 31141940, 2019). "Using P‐values <0.05 as selection criteria, the variables with statistically significant associations with CRF were TNF‐α, anxiety, depression, insomnia, age, menopausal status and type of chemotherapy." (PMID 31016867, 2019). "WEC have been found to prevent not only the production of TNF-α and IL-6 in activated brain microglial cells/macrophages, but also neuroinflammation associated with fatigue, depression, and memory impairment in animal studies." (PMID 31394768, 2019). "Direct injection of inflammatory cytokines, such as TNF-α and IL-1β, into the brain of animals can produce depression-like behaviors, such as loss of pleasure, decreased activity, and decreased food intake." (PMID 31141940, 2019). "Symptoms of depression are often caused by pro-inflammatory cytokines, mainly due to tumor necrosis factor α (TNF-α), interleukin 1 beta (IL-1β), and interleukin 6 (IL-6)." (PMID 31771312, 2019). "Previous studies have also reported that TNF-alpha was involved in the development of inflammation-associated depressive disorder 50,51." (PMID 31754388, 2019). "The degree of depression was associated with the levels of IL-1β, TNF-α, and IL-8, while the degree of comorbidity between depression and anxiety was associated with the IL-8 level." (PMID 29856741, 2018). "Studies found that elevated levels of cytokines such as interleukin- (IL-) 1β, IL-6, and tumor necrosis factor-α (TNF-α) are closely associated with the pathogenesis of depression." (PMID 29765402, 2018). "In a recent investigation carried out by Mrugacz and colleagues, the concentrations of the pro-inflammatory cytokines IL-17 and TNF-α in tears were associated with the clinical severity of dry eye disease in patients with depression." (PMID 30096194, 2018). "Our results indicate that changes in the levels of cytokines (such as IL-1β, TNF-α, and IL-8) were associated with the degree of depression." (PMID 29856741, 2018). "Maternal stress and depression have both been associated with higher circulating levels of IL-6 and TNF-α across pregnancy." (PMID 30200631, 2018). "In fact, a recent systematic review and meta-analysis validated the effect of anti –TNF-α drugs in improving depression symptoms, and associated the antidepressant effect with baseline symptom severity." (PMID 29515447, 2018). "Sleep loss, for instance, is known to induce proinflammatory markers CRP, Interleukin-6 (IL-6) and TNF that are associated with depression and obesity." (PMID 30524737, 2018).
depression (continued). "Our study found that supplementation with EPA-rich fish oil in particular resulted in reduced concentrations of IL6 and TNFα, inflammatory cytokines that have been associated with major depression in other studies." (PMID 29940888, 2018). "Depression is associated with increased concentration of proinflammatory cytokines in circulation, such as IL-1β, IL-6, TNF-α, IFN-γ, and chemokines." (PMID 29351245, 2018). "Firstly, TNF polymorphism (rs1799724) has a predominant effect on the structure of the visual cortex in the presence of depression." (PMID 30310056, 2018). "Our findings demonstrate that a polymorphism, which is potentially linked to higher transcription of TNF-α, is associated with structural changes in the occipital cortex, especially in the presence of depression." (PMID 30310056, 2018). "Depression has therefore been associated with high levels of IL-6, TNF-α, IL-1 beta, C-reactive protein (CRP), chemokines, and adhesion molecules." (PMID 29619128, 2018). "TNF-α is known to be increased in anxiety disorder, posttraumatic stress disorder and major depression, where TNF-α and IL-6 are also associated with a smaller chance to respond to treatment with SSRIs." (PMID 30241502, 2018). "In terms of immune dysregulation, depression has been associated with both immune activation (increase in pro-inflammatory mediators such as IL-6, TNF-α, CRP, IL1) and immune suppression (loss of T cell and NK cell function) (reviewed)." (PMID 29894487, 2018). "In inflammatory bowel disease (IBD), immune activation with increased circulating TNF-α is linked to the intensity of gastrointestinal symptoms and depression or anxiety." (PMID 29518097, 2018). "Changes in the tumor necrosis factor‐α (TNFα) have been associated with major depressive disorder (MDD)." (PMID 29670819, 2018). "Thirdly, it is possible that there are other potential confounding factors mediating the observed relationship between TNF polymorphism and brain structure in depression." (PMID 30310056, 2018). "A double-blind, placebo-controlled, randomized trial with anti-TNFα Ab infliximab in 60 patients with major depression showed an association between baseline levels of the inflammatory marker CRP and the response to infliximab." (PMID 30423923, 2018). "In another study, the TNF-α 308A allele was also found to be associated with post-stroke depression." (PMID 27555379, 2017). "We identified one further study concerning the TNF-α A-308G polymorphism (rs1800629) in relation to IFN-α-induced depression: the authors found a significant association with labile anger and fatigue but not with depression." (PMID 27555379, 2017). "TNF-α, IL-6, and IL-10 also played important roles in depression induced by stress, which caused the increase of proinflammation cytokines, including TNF-α, IL-6, and IL-1β in serum and hippocampus." (PMID 28694833, 2017). "The less-well investigated TNF-α SNP rs1800610 was associated with a cluster of fatigue, sleep disturbance, and depression in breast cancer patients when carrying one or both of the rare T alleles." (PMID 27555379, 2017). "Depression has been linked to a pro-inflammatory response, because cytokines like interleukin 6 (IL-6) and tumor necrosis factor alpha (TNF) are increased." (PMID 29403374, 2017). "Elevated CSF IL-6, IL-8, and TNF seem to have the strongest associations with depression, apathy, and disinhibition at 6–12 months." (PMID 28740480, 2017). "Analysis of the Neuropsychiatric inventory (NPI) from the same cohort showed that elevated systemic TNF-α was associated with a 2-fold increase in symptoms characteristic of sickness behavior including apathy, anxiety, depression and agitation." (PMID 27633985, 2017). "In this paper, we address these questions by measuring the serum levels of two common metabolic risk factors of AD and depression, inflammatory cytokines (IL 6 and TNF alpha) and serum 25-hydroxyvitamin D, in a case-control study." (PMID 28580183, 2017).
depression (continued). "Proinflammatory cytokines, such as TNFα, have been implicated in the pathophysiology of dementia and depression." (PMID 28629481, 2017). "Analyzing male and female offspring together, only the concentration of maternal TNF-α was significantly associated with depression risk in the offspring." (PMID 27244231, 2016). "After adjustment for baseline history of depression, the baseline RE score was found to be independently and negatively associated with the levels of IL-8 and TNF-α (both P < 0.02)." (PMID 27861337, 2016). "Our finding that the depression risk after exposure to higher prenatal TNF-α:IL-10 levels was restricted to male offspring is consistent with this prior work in male animal models." (PMID 27244231, 2016). "In particular, evidence suggests that depression is associated with increased circulating concentrations of proinflammatory cytokines such as IL-1β, IL-6, TNF-α, and IFN-γ in association with elevations in chemokines and the acute phase protein, CRP." (PMID 26775294, 2016). "The EM score was found to be independently and negatively associated with history of depression and the level of TNF-α (all P < 0.05)." (PMID 27861337, 2016). "Among female offspring, in utero exposure to higher TNF-α levels relative to IL-10 was associated with a lower risk of depression (OR=0.51; CI=0.32, 0.81)." (PMID 27244231, 2016). "Dysregulation of TNF production has been linked to a variety of human diseases including Alzheimer’s disease, major depression and cancer." (PMID 27391163, 2016). "High maternal TNF-α was associated with reduced odds of depression among both male and female offspring (odds ratio (OR)=0.68; confidence interval (CI)=0.48, 0.98)." (PMID 27244231, 2016). "Longitudinal studies are necessary to determine the causal relationship between TNF-α and depression in SLE patients." (PMID 26732584, 2016). "Meta-analyses have also supported depression’s associations with IL-1β and TNF-α as well as sIL-2 receptor." (PMID 28082989, 2016). "There are other potential reasons for the association between lower TNF-α and offspring's risk of depression." (PMID 27244231, 2016). "Then, we focus on the more extensive rodent and human primate literature to illustrate the pathogenesis, susceptibility and therapeutic role of TNF-α in depression." (PMID 27187381, 2016). "Only TNF-α levels showed an association with incident depression, with this association having a U-shaped form." (PMID 27918465, 2016). "In contrast, among male offspring, exposure to higher maternal TNF-α levels relative to IL-10 was associated with a higher risk of depression (OR=1.86; CI=1.02, 3.39)." (PMID 27244231, 2016). "The upregulation of the HPA axis is an important finding associated with depression, highlighting the potential for direct clinical significance of raised proinflammatory cytokines, mainly TNF-α." (PMID 26732584, 2016). "We identified one further study concerning the TNF-α A-308G polymorphism (rs1800629) in relation to IFN-α induced depression." (PMID 27187381, 2016). "Our results demonstrating that higher pro-inflammatory:anti-inflammatory drive (TNF-α:IL-10 ratio) in maternal serum was associated with a lower risk for depression in female offspring were unexpected." (PMID 27244231, 2016). "In the case of storage LUTS, this effect on incident depression was associated with higher TNF-α, whereas the effect of voiding LUTS on incident anxiety was independent of elevated e-Selectin." (PMID 26445118, 2015). "Of the inflammatory markers studied in the present study, CRP, IL–6 and TNF- α have been previously shown to have an association with depression / anxiety." (PMID 26445118, 2015). "These positive associations were maintained in multi-adjusted models of depression and anxiety for both TNF-α and e-Selectin." (PMID 26445118, 2015). "Several clinical observations suggest that TNF-α is one of the key cytokines contributing to the development of inflammation-associated depression." (PMID 26290874, 2015).
depression (continued). "There are several indications that tumor necrosis factor-α (TNF-α) is one of the key cytokines involved in the pathogenesis of inflammation-associated depression." (PMID 26290874, 2015). "Severe depression was more strongly associated with IL-6, CRP and TNF-α compared to moderate depression." (PMID 26065825, 2015). "First, depression has been positively associated with high systemic levels of inflammatory mediators (especially IL-4, IL-6 and TNF-a), which have underlying pathogenic roles in asthma." (PMID 26197472, 2015). "Such chronic TNF-α administration would mimic the human situation where inflammation-associated depression is believed to develop on a background of sustained, low-grade inflammation." (PMID 26290874, 2015). "Development of depression is also associated with elevated circulating concentrations of inflammatory biomarkers; for example, proinflammatory and antiviral cytokines (IL-2, TNF-α and IFN-α) have been associated with flu-like and depressive symptoms." (PMID 25237578, 2014). "Compared to age-matched controls, patients diagnosed with major depression showed elevated levels of transmembrane TNFα (tmTNFα) in BA46, a region associated with emotion regulation." (PMID 25364500, 2014). "The deregulation of TNF-α production has been implicated in infectious disease and in a variety of human diseases including cancer, Alzheimer's disease, major depression, and inflammatory bowel disease." (PMID 24868535, 2014). "LPS-induced depression was associated with increments in IL-1β content in plasma and prefrontal cortex, TNF-α in plasma, and decreased nitrergic neurotransmission evident in the striatum and prefrontal cortex." (PMID 24999483, 2014). "Even extremely low doses of TNF-α administered ICV causes depression-like behavior as assessed as increased time of immobility during both the FST and tail suspension test." (PMID 23634700, 2013). "As the SCL-90 depression score was most sensitive to mood changes after infusion of anti-TNF-α, the association between mood changes and immune parameters was examined in more detail." (PMID 23544139, 2013). "Activated microglia employ IL-6 and TNF-α as antineurogenic signals, which can interact directly with neural progenitor cells via TNF and IL-6 receptors causing a decrease in neurogenesis, and also in emotion-regulating brain structures involved in depression." (PMID 23672628, 2013). "IL-6 and TNFα, pro-inflammatory cytokines commonly associated with depressive disorders, were found to be increased in cultured neurons, especially after costimulation." (PMID 24391741, 2013). "Depression has been found to be associated with elevated levels of interleukin-1 (IL-1), IL-6, and tumor necrosis factor-α (TNF-α)." (PMID 22830072, 2012). "Our findings are mainly in line with a study by Menza and colleagues in which a significant association between plasma TNF-α and depressive symptoms was found in a group of PD patients with ongoing depression." (PMID 23082161, 2012). "To date, the C677T variant of MTHFR is associated with both susceptibility to depression and ethanol response, and levels of TNF mRNA have been associated with depression." (PMID 18822146, 2008). "Recent genetic research points at the importance of caspase genes for the predisposition to major depression, and caspases are one intracellular signaling way of TNF-α signaling." (PMID 19506720, 2008). "In our model, MGO not only elevated depression-related markers such as GR and cortisol but also increased free MGO and pro-inflammatory cytokines (IL-1β, IL-6, TNF-α), implicating activation of inflammatory pathways that underlie psychoneuroimmunity-related depression." (PMID 41355970, 2026). "Moreover, high levels of IL-6 were associated with a rapid progression of depressive symptoms in patients, and TNF-α was also linked to worsening depression." (PMID 41601490, 2026).
depression (continued). "The study revealed that factors like marital status, the use of anti‐tumor necrosis factor agents, age, body mass index, disease activity, alcohol consumption, and employment status were linked to increased levels of depression and anxiety in individuals with IBD." (PMID 40927042, 2025). "Pro-inflammatory cytokines such as interleukin-1 (IL-1), tumor necrosis factor alpha (TNF-α), and interleukin-6 (IL-6) have been linked to neuroinflammation in illnesses such as Alzheimer’s disease (AD), Parkinson’s disease (PD), depression, and multiple sclerosis (MS)." (PMID 39861166, 2025). "Furthermore, a recent, crossover and prospective study (with 5 years of follow-up) documented that elevated blood levels of inflammatory cytokines (TNF, IL-17) are positively associated with the presence of depression in women." (PMID 40141399, 2025). "Additionally, prenatal discrimination is associated with postnatal anxiety and depression mediated by TNF-α methylation." (PMID 40766923, 2025). "Stress, a common factor in the development of depression and depressive-like behaviors, causes to activate the M1 phenotype of microglia and synthesize pro-inflammatory cytokines (IL- 6, IL- 1β and TNF-α) and oxidative mediators (ROS and NO), and these mediators are abundant in depressed patients." (PMID 40281288, 2025). "The pathogenesis of depression in numerous psychiatric disorders is characterized by chronic inflammation, which is associated with elevated levels of proinflammatory cytokines (such as TNF and IL-6)." (PMID 41463013, 2025). "IL-10, another key anti-inflammatory cytokine, suppresses the production of pro-inflammatory mediators such as TNF-α and IL-1β, while enhancing tissue regeneration and immune homeostasis.In depression-related studies, elevated IL-4 levels have been associated with better emotional stability." (PMID 40453075, 2025). "In a chronic stress scenario, indeed, norepinephrine and cortisol overproduction can activate microglia and mast cell trough NLRP3 inflammasome, with release of pro-inflammatory cytokines, such as IL-1β and TNF-α, and Reactive Oxygen Species (ROS), causing neuroinflammation and depression." (PMID 40141399, 2025). "Depression is a multifaceted disorder caused by neuroinflammation, which is mainly demarcated by a significant increase in proinflammatory cytokines, including interleukin-1β (IL-1β), interleukin-6 (IL-6), and tumor necrosis factor-α (TNF-α)." (PMID 40487411, 2025). "In particular, individuals with poor emotional regulation or low sleep quality were more vulnerable to the negative effects of elevated inflammatory markers, such as CRP, IL-6, and TNF-α, associated with greater fatigue, somatic complaints, depression, and anxiety." (PMID 41333345, 2025). "In addition, qPCR analysis showed an upregulation in the expression of inflammatory markers like IL‐1β, TNF‐α, and the depression‐associated gene SLC6A4 after hormonal treatment and TBI exposure." (PMID 39665190, 2025). "TNF-α is also an important cytokine involved in HIV-associated depression." (PMID 40313235, 2025). "The study's limitations include a small sample size of UC patients, the lack of analysis of gut microbiota composition and fecal butyrate levels, and the omission of key inflammatory cytokines such as IL-6 and TNF-α as well as some potential diagnostic biomarkers for depression such as BDNF." (PMID 40123849, 2025). "Elevated cytokines such as IL-10, IL-1β, and TNF-α are linked to common comorbidities of depression, including hypertension and diabetes, and may serve as potential markers of disease severity and treatment response." (PMID 41226736, 2025). "TNF-α, positively linked to depression, concurrently elevates somatic fatigue." (PMID 40697716, 2025). "According to evidence, increasing levels of inflammatory markers such as IL-1β, IL-6, and TNF-α may be associated with depression." (PMID 40487411, 2025).